BRCA2 (BRCA2 DNA repair associated)
Diseases named in the same sentence as BRCA2 in open-access papers (continued):
Sharing a sentence is not in itself a finding about the gene and the disease.
breast cancer (continued). "Similar to the role of mutations in BRCA1/2 in the development of breast cancer and ovarian cancer, various studies have shown that inactivating BRCA1/2 mutations, predominantly BRCA2, increase predisposition to PCa." (PMID 31197228, 2020). "Partner and localizer of BRCA2 (PALB2) is essential to homologous recombination repair in response to double-stranded breaks in DNA4 and is a more recently identified breast cancer predisposing gene." (PMID 32300229, 2020). "In the last decade of the twentieth century, 2 major predisposing genes susceptibility to breast cancer, BRCA1 and BRCA2 were identified through the genetic linkage mapping and the positional cloning." (PMID 32080114, 2020). "We studied germline genetic variants associated with the survival of breast cancer patients carrying pathogenic variants in the high-risk BRCA1 and BRCA2 genes." (PMID 32964118, 2020). "Large-scale analyses of multigene panel testing recently confirmed PALB2 as a high-risk breast cancer susceptibility gene, and the odds ratio (OR) of PALB2 mutations for breast cancer was comparable to that of BRCA2 mutations." (PMID 32185139, 2020). "The BRCA2 level has been shown to be reduced in tumor gland samples, suggesting that low expression of BRCA2 is contributing to mammary tumor development in dogs." (PMID 32005245, 2020). "BRCA1 and BRCA2 are highly penetrated genes involved in the familial breast cancer development and about 15 % of all familial breast cancer can be attributed to a mutation in these genes." (PMID 33013205, 2020). "We used clinical and molecular data from 1101 TCGA breast-cancer patients to evaluate the downstream effects of BRCA1 and BRCA2 germline mutations in tumors." (PMID 32997669, 2020). "BRCA2 c.9976A>T; p.K3326X, which we identified in three European American breast cancer cases, is classified as likely benign according to the ACMG guidelines." (PMID 32866190, 2020). "On the other hand, the breast cancer susceptibility genes, BRCA1 and BRCA2, also known as FANCS and FANCD1, respectively, are involved in the FA pathway; hence, researchers have studied the association between the FA pathway and cancer predisposition." (PMID 32300589, 2020). "Reliable estimation of the association between uptake and timing of RRSO and breast cancer risk is critical for informing counselling and clinical management of BRCA1 and BRCA2 mutation carriers." (PMID 31948486, 2020). "Nearly 5% of breast cancers occur in a context of genetic predisposition, mostly represented by monoallelic pathogenic variants of BRCA1, BRCA2 or PALB2 genes." (PMID 33302444, 2020). "Clinical factors associated with BRCA1 pathogenic variants included a family history of breast cancer and hormone receptor status of the tumor, while for BRCA2, the only statistically significant clinical factor was a family history of breast cancer." (PMID 32318955, 2020). "High-penetrance breast cancer susceptibility genes, such as BRCA1 and BRCA2, explain only a small fraction of breast cancers in the general population because of their low carrier rates." (PMID 33226082, 2020). "The present study assessed the proportion of recently diagnosed, high risk, breast cancer patients treated in a US community oncology setting, who were tested for BRCA1/BRCA2 variants in accordance with NCCN guidelines." (PMID 32518611, 2020). "The breast cancer susceptibility genes (BRCA1 and BRCA2) encode proteins critically involved in the repair of DNA double-strand breaks." (PMID 33109210, 2020). "About 70% of breast cancers in BRCA1 mutation carriers and up to 23% of BRCA2 carriers are triple-negative." (PMID 33282730, 2020).
breast cancer (continued). "The cumulative breast cancer risk at 40 years of age is approximately 24% for BRCA1 carriers and 13% for BRCA2 carriers." (PMID 32419845, 2020). "The most important risk factors for breast cancer include female gender, age (30 years old and older), positive family history for breast cancer, and familial genetic mutations, including mutations in the breast cancer A1 (BRCA1) and BRCA2 genes." (PMID 32964011, 2020). "The FA pathway constitutes a part of the DNA-damage network, including breast cancer-susceptibility proteins BRCA1 and BRCA2." (PMID 32708070, 2020). "Data from the Cancer Genome Atlas Program (TCGA) show that ∼ 20% of basal-like breast cancers have a germline and/or somatic BRCA1 or BRCA2 variant." (PMID 33109210, 2020). "TNBC accounts for about 70% and 16–23% of BRCA1 and BRCA2 mutation carriers, respectively, suggesting that TNBC is also inextricably linked to germline mutation in this breast cancer susceptibility gene." (PMID 31998560, 2020). "The cumulative risk of developing breast cancer (BC) to the age of 80 years for heterozygotes of BRCA1 and BRCA2 pathogenic variants (hereafter, heterozygotes), has been approximated at 72% (95% CI 65–79%) and 69% (95% CI 61–77%), respectively." (PMID 32375709, 2020). "From the point of breast cancer risk and radiation sensitivity, it would be reasonable to screen BRCA1 and BRCA2 mutation carriers according to the same protocol." (PMID 32333294, 2020). "Risk-reducing salpingo-oophorectomy (RRSO) provides an important reduction in ovarian and breast cancer risks and related mortality; however, the latter is less clearly demonstrated for BRCA2." (PMID 32655641, 2020). "Basal-like breast cancers commonly carry mutations in genes linked with DNA repair mechanisms like BRCA1, BRCA2, or RAD51." (PMID 33261142, 2020). "We genotyped 2464 women with breast cancer diagnosed below age 41 years for twenty recurrent germline mutations in six genes, including BRCA1, BRCA2 CHEK2, PALB2, NBN, and RECQL." (PMID 32824581, 2020). "Breast cancer susceptibility gene (BRCA1 and BRCA2) mutations, which confer substantial lifetime risks of breast and ovarian cancers, influence oncogenesis and metastasis of breast cancer." (PMID 31998560, 2020). "The first discovered breast cancer predisposition genes, BRCA1 and BRCA2 also turned out to be FANC genes, named FANCS and FANCD1." (PMID 32725171, 2020). "In the total sample, only few breast cancer-free women (462; 1.3%) were tested for BRCA1 and/or BRCA2 germline pathogenic variants, including both complete and targeted testing." (PMID 32565540, 2020). "The Breast Cancer Susceptibility Genes, BRCA1 and BRCA2, have well established roles in the maintenance of genomic stability." (PMID 33015058, 2020). "The most common germline mutated DDR genes in primary PCa or CRPC are found in the Breast Cancer 1 and 2 (BRCA1 and BRCA2) genes." (PMID 31197228, 2020). "On the other hand, in BRCA2 carriers from CIMBA, RA showed an increased risk of breast cancer, despite a statistically insignificant result (OR: 1.07, 95% CI: 0.99–1.15)." (PMID 33167385, 2020). "Of the 211 BRCA1/2 carriers diagnosed with breast cancer (with MF/MC information available) in Northern Ireland between 1994 and 2017, 90 (42.7%) women had a BRCA1 mutation and 121 (57.3%) a BRCA2 mutation." (PMID 32022473, 2020). "Published data had shown that 5–10% of breast cancer is hereditary and mostly related to BRCA1 or BRCA2 gene mutations." (PMID 32733560, 2020).
breast cancer (continued). "Similar results were shown in another study demonstrating a 10-year cumulative contralateral breast cancer risk of 23.9% (BRCA1: 25.5%; BRCA2: 17.2%) in patients <41 years, compared to 12.6% in the 41–49 year group (BRCA1 15.6%; BRCA2 7.2%)." (PMID 31935898, 2020). "We have studied survival associations of genetic variants in two etiologically unique groups of breast cancer patients, the carriers of germline pathogenic variants in BRCA1 or BRCA2 genes." (PMID 32964118, 2020). "To date, multiple breast cancer predisposition genes have been identified, mainly from studies of women of European ancestry, including BRCA1, BRCA2, PALB2, CHEK2, and ATM, which together accounted for 25% of the familial risk." (PMID 32318955, 2020). "Pathogenic variants in the tumor suppressor breast cancer genes BRCA1 and BRCA2 increase the risk of female breast and ovarian cancers." (PMID 32518611, 2020). "At the same time, we analyzed the difference in patients with breast cancer and ovarian cancer mutated in BRCA1 or BRCA2 or who were wild-type." (PMID 32195358, 2020). "BRCA2, which is commonly deleted in heritable breast cancer, functions in DNA double strand break repair and centrosome clustering." (PMID 32681145, 2020). "There are twenty recurrent mutations in six breast-cancer-predisposing genes in Poland (BRCA1, BRCA2, CHEK2, PALB2, NBN, and RECQL)." (PMID 32824581, 2020). "The germline mutation rate of the members of the Fanconi anemia gene family (including BRCA2, PALB2, and RAD51C) was 25.93% (7/27) among patients with germline mutations in TNBC, which was lower than those in unselected breast cancer." (PMID 33194720, 2020). "During the 25 year period since the BRCA1 and BRCA2 genes were identified, a number of additional breast cancer genes have been identified." (PMID 31963545, 2020). "Up to half of the heritable mutations in breast cancer (BC) are attributed to BRCA1 and BRCA2 genes." (PMID 32102521, 2020). "In conclusion, the efficacy of risk-based breast cancer screening practices, such as MRI, for BRCA1 and BRCA2 mutation carriers shows promise in terms of increased cancer detection rates and decreased mortality." (PMID 31734900, 2020). "Among early onset breast cancer patients who were diagnosed before 35 years of age, prevalence of germline variants in BRCA1, BRCA2, and other genes was 9.8%, 17.1%, and 4.9%, respectively." (PMID 33067557, 2020). "BRCA1 and BRCA2 are two highly penetrant genes involved in the inherited breast cancer and contribute to different DNA damage pathways and cell cycle and apoptosis cascades." (PMID 33013205, 2020). "Patients with loss-of-function of the BRCA1 or 2 proteins have a higher cumulated breast cancer risk, with a cumulated lifetime risk at eighty years old of 72% (BRCA1) and 69% (BRCA2)." (PMID 33302444, 2020). "Both breast cancer 1 and breast cancer 2 (BRCA1 and BRCA2) genes are prone to mutation, thought to be due to high densities of repetitive DNA elements." (PMID 32403357, 2020). "The cumulative incidence of breast cancer by age 70–80 years in female mutation carriers is 71.4–87% for the BRCA1 mutation and 77–88% for the BRCA2 mutation." (PMID 32322271, 2020). "While PIK3CA alterations occur in 36% or more of breast cancer patients there are other relevant biomarkers to consider in these patients, including ERBB2, BRCA1, BRCA2, NTRK, and MSI (or mismatch repair deficiency)." (PMID 32976510, 2020). "Regular use of aspirin and other non-steroidal anti-inflammatory drugs (NSAIDs) has been consistently associated with reduced risk of cancers, including breast cancer, and reduced breast cancer risk in high-risk women with BRCA1 and BRCA2 mutations." (PMID 32731638, 2020).
breast cancer (continued). "For example, miR-146a and the G allele of rs2910164 have been correlated with breast cancer risk (odds ratio (OR) = 1.77; 95% confidence interval (CI) = 1.40–2.23) as its predicted binding sites are 3′ untranslated regions of BRCA1 and BRCA2." (PMID 32823908, 2020). "Third, gene markers of breast cancer like BRCA1 and BRCA2, are used to stratify patients based on the risk for disease." (PMID 32144248, 2020). "BRCA1 and BRCA2 are two highly penetrant genes involved in inherited breast cancer and contribute to different DNA damage pathways and cell cycle and apoptosis cascades." (PMID 33013205, 2020). "In our study, TNBCs account for 25% of all BRCA-variant breast cancers present in probands: 70% of these was related to BRCA1 PVs and 30% was associated to BRCA2 PVs." (PMID 32380732, 2020). "A subsequent study utilised skin biopsies of 30 (10 BRCA1, 10 BRCA2 and 10 sporadic) women with a history of breast cancer who were disease free at time of recruitment." (PMID 33081408, 2020). "Breast cancer risk is elevated up to 72% for BRCA1 and up to 69% for BRCA2 mutation carriers, respectively." (PMID 32719921, 2020). "Germline pathogenic alterations in the breast cancer susceptibility genes 1 (BRCA1) and 2 (BRCA2) are the most prevalent causes of hereditary breast and ovarian cancer (HBOC)." (PMID 32655641, 2020). "The effect of risk-reducing salpingo-oophorectomy (RRSO) on breast cancer risk for BRCA1 and BRCA2 mutation carriers is uncertain." (PMID 31948486, 2020). "Intriguingly, in contrast to BRCA2, BRCA1 mutations are thought to contribute to more cases of early onset breast cancer." (PMID 33505905, 2020). "Of interest, such scars are also observed in tumors deficient for the breast cancer genes BRCA1 and BRCA2 (COSMIC mutational signature ID6)." (PMID 32330130, 2020). "In the primary analysis, the hazard ratio (HR) for the association between RRSO and breast cancer risk was 1.23 (95% CI 0.94–1.61) for BRCA1 and 0.88 (95% CI 0.62–1.24) for BRCA2 mutation carriers." (PMID 31948486, 2020). "It was reported that the risk of breast cancer increased substantially between the ages of 30 and 50 years for BRCA1 carriers, while the risk was highest between the ages of 40 and 60 years for BRCA2 carriers, which was simulated to our results." (PMID 31912664, 2020). "Similar to that in many BRCA1- and BRCA2-associated tumors, many PALB2-associated breast cancers (i.e., 67%) show loss of the PALB2 wild type allele via acquired pathogenic somatic variants, or via loss-of-heterozygosity (LOH)." (PMID 33195396, 2020). "Control women were more likely than cases to have a family history of breast cancer, BRCA1 and BRCA2 mutations, a history of LCIS and a history of benign breast disease." (PMID 33287857, 2020). "Although recent efforts examining polygenic risk of breast cancer have focused on common variants, rare variants that modify risk in BRCA1 and BRCA2 mutation carriers have been identified." (PMID 32866190, 2020). "BRCA1 and BRCA2 are the most commonly tested genes in individuals presenting with early-onset breast cancer, triple-negative breast cancer, bilateral breast cancer and familial breast/ovarian cancer." (PMID 32468491, 2020). "Genotyping BRCA1, BRCA2, and PALB2 French-Canadian breast cancer variants identified a pathogenic variant in 3.8% (21/555) of breast cancer cases unselected for age or family history and 0.2% (5/1940) of cancer-free controls." (PMID 32300229, 2020). "The cumulative risk of breast cancer at age 80 is estimated at 72% for BRCA1 carriers and 69% for BRCA2 carriers, while for ovarian cancer it is estimated at 44% for BRCA1 carriers and 17% for BRCA2 carriers." (PMID 32025337, 2020). "There were 338 germline BRCA mutation carriers in the POSH study breast cancer cohort; focality data were missing in 37 cases, leaving 180 women with a BRCA1 mutation and 121 with a BRCA2 mutation for analysis." (PMID 32022473, 2020).
breast cancer (continued). "In this cohort, the proportion of young women with breast cancer before the age of 35 years was lowest for both BRCA1 and BRCA2 mutation carriers (14.1 and 8.2%, respectively)." (PMID 32140806, 2020). "In our manuscript we report a novel BRCA2 duplication of exons 22–24 in a female patient with bilateral breast cancer." (PMID 31724318, 2020). "The young age for development of breast cancer often suggests a genetic predisposition especially germline mutations in BRCA1 and BRCA2 genes." (PMID 32894085, 2020). "Variants more prevalent in the French-Canadian population have been identified in established breast cancer predisposition genes BRCA1, BRCA2, and PALB27–14." (PMID 32300229, 2020). "In our previous study, twenty recurrent mutations were found in six breast-cancer-predisposing genes (BRCA1, BRCA2, CHEK2, PALB2, NBN, and RECQL) in Polish breast cancer patients." (PMID 32824581, 2020). "We investigated the associations between a recently reported PRS for breast cancer, based on 313 SNPs, and a PRS for EOC, based on 30 SNPs, with cancer risks for BRCA1 and BRCA2 carriers." (PMID 32665703, 2020). "Above age 70 to 75 years, the cumulative risk of breast cancer and ovarian cancer among BRCA1 and BRCA2 mutation carriers stabilizes." (PMID 32882684, 2020). "We found that the mutation frequency of ERCC6 (1.8%) in breast tumors was similar to those of known breast cancer susceptibility genes, such as BRCA1 (2.9%), BRCA2 (2.9%), BLM (1.9%), FGFR2 (1.5%), and CHEK2 (1.0%)." (PMID 33277540, 2020). "The 10-year occurrence rates of breast cancer among patients with prior ovarian cancer were 12% in BRCA1 mutation carriers and 2% in BRCA2 mutation carriers." (PMID 32250967, 2020). "The discovery of the second breast cancer predisposing gene was followed by the BRCA1 cloning, and subsequently, the race to clone BRCA2 was completed the following year by the same research team." (PMID 32269964, 2020). "For BRCA2 carriers, PRSBC was associated with breast cancer risk with a per SD HR = 1.36 (95% CI = 1.17–1.57, P = 4.3×10−5)." (PMID 32665703, 2020). "The break on chromosome 2 was located in an intron of ENSSSCG00000032003, which is an ortholog of the human BRCA2 gene, a breast cancer gene involved in DNA repair (OMIM entry 600,185;)." (PMID 32831014, 2020). "Approximately 10-15% of breast cancer cases are caused by hereditary genetic mutation of BRCA1 and BRCA2 genes." (PMID 32856854, 2020). "While germline BRCA1/2 mutations occur in 5.3% of unselected breast cancers according to The Cancer Genome Atlas (TCGA), a recent study showed that 11.2% of unselected TNBC cases had deletions in the BRCA1 (8.5%) and BRCA2 (2.7%) respectively." (PMID 33282730, 2020). "The clinical utility of GWAS in determining those high-penetrance breast cancer gene mutations was initially very high back in the 1990s, when BRCA1 and BRCA2 were first cloned." (PMID 32823908, 2020). "Our preliminary results showed that in young Rwandan patients with breast cancers, BRCA genes were the most mutated with a predominance of BRCA2 variants." (PMID 32959997, 2020).